MIR767 (microRNA 767)
Synonyms: hsa-mir-767; MIRN767; mir-767
Gene: MicroRNA gene on chromosome X (152,393,421 to 152,393,529, reverse strand). Ensembl gene ENSG00000211583.
Gene Ontology:
Biological process: miRNA-mediated post-transcriptional gene silencing
Homologues: Orthologues: chimpanzee ptr-mir-767 (100% identical), macaque mml-mir-767 (99% identical), guinea pig MIR767 (85% identical).